SNX10 (sorting nexin 10)
Diseases named in the same sentence as SNX10 in open-access papers (continued):
Sharing a sentence is not in itself a finding about the gene and the disease.
tumor (12 papers, 2018 to 2025). "Although our current study focused primarily on macrophage-driven changes in the tumor microenvironment, the potential role of SNX10 in regulating cancer-associated fibroblasts and broader stromal remodeling permits further study." (PMID 40810725, 2025). "The present study confirmes that SNX10 deficiency enhanced CMA through the LAMP-2A mediated signaling in CRC tumor cells." (PMID 29867114, 2018). "Upregulated expression of SNX10 may signify a highly active state of tumor cells, associated with increased aggressiveness or a higher probability of recurrence." (PMID 40341994, 2025). "Our study also demonstrates that over-activated CMA by SNX10 deficiency was responsible for the upregulated amino-acid metabolism and mTOR signaling activation; eventually promoted the abnormal growth and proliferation of tumor cells." (PMID 29867114, 2018). "IHC analysis further confirmed that SNX10 depletion enhances desmoplasia, inflammation, and tumor proliferation." (PMID 40810725, 2025). "Together, these findings establish SNX10 as a novel candidate tumor suppressor in PDAC, potentially antagonizing KRAS oncogenic function." (PMID 40810725, 2025). "Lentivirus-mediated SNX10 overexpression in THP-1 cells was employed in tumor cell–macrophage co-culture experiments." (PMID 40426851, 2025). "Collectively, these findings highlight SNX10 as a tumor suppressor candidate in PDAC and underscore its promise as a foundation for new therapeutic approaches." (PMID 40810725, 2025). "Further studies are required to elucidate how SNX10-overexpressing macrophages modulate tumor cell behavior." (PMID 40426851, 2025). "In this study, we define a novel role of sorting nexin 10 (SNX10) as a candidate tumor suppressor in PDAC." (PMID 40810725, 2025). "This study establishes SNX10 as a tumor suppressor candidate in PDAC, with its loss contributing to increased tumor growth, aggressiveness, and reduced survival." (PMID 40810725, 2025). "Altogether, our results demonstrated that the loss of SNX10 significantly reduced mice survival, modified the PDAC tumor microenvironment, and promoted tumor proliferation, thus further supporting the tumor suppressor function of this molecule in PDAC biology." (PMID 40810725, 2025). "SNX10 manifested a tumor suppressing influence by regulating autophagy behavior of tumor cells to inhibit the progress of colorectal cancer." (PMID 35715463, 2022). "This was confirmed via in vitro analysis as well as mouse models, which showed an increase in tumor cell proliferation and viability upon SNX10 downregulation, which can be reversed upon exogenously increasing the expression levels of SNX10." (PMID 36612066, 2022). "The validation in GEO showed that PTGDS showed low expression while SNX10 presented high expression in tumor tissues." (PMID 34116656, 2021). "According to GEO validation results, PTGDS was lowly expressed and SNX10 highly expressed in tumor tissues, which was consistent with the results from immunohistochemistry." (PMID 34116656, 2021). "The results showed that PTGDS had high expression levels in normal tissues and low expression levels in tumor tissues, while SNX10 showed an opposite profile." (PMID 34116656, 2021). "Here we investigated the role of SNX10 in regulating amino-acid metabolism and mTOR signaling pathway activation, as well as the impact on the tumor progression of mouse CRC." (PMID 29867114, 2018). "Through regulating chaperone-mediated autophagic degradation of p21Cip1/WAF1, SNX10 acts as a tumor suppressor in tumorigenesis and progression of colorectal cancer." (PMID 29867114, 2018). "Correspondingly, the tumor load, which represents the sum of the diameters of all tumors in a given mouse, was significantly increased in SNX10 KO mice." (PMID 29867114, 2018). "This study identifies SNX10 as a novel tumor suppressor candidate in PDAC." (PMID 40810725, 2025).
tumor (continued). "In B-ALL, the expression of SNX10 may be influenced by the tumor microenvironment, leading to its reduced expression in tumor cells." (PMID 40341994, 2025). "However, in SNX10 KO mice the number of tumors increased almost two times and the tumor sizes were larger compared to WT mice." (PMID 29867114, 2018). "Our data suggest that SNX10 deficiency enhanced CMA-mediated degradation of targeted proteins to increase specific amino acids, and subsequently activated mTORC1 to facilitate the tumor progression." (PMID 29867114, 2018). "Future studies should focus on investigating SNX10 expression and its correlation with clinical outcomes in samples from patients with PDAC as well as to identify its direct molecular targets and determining whether restoring SNX10 function can effectively inhibit tumor progression." (PMID 40810725, 2025). "We observed that SNX10 OE in human PDAC cells significantly reduced cell proliferation, tumor initiation, and protumorigenic protein activity." (PMID 40810725, 2025). "Using a novel Snx10 knockout mouse crossed with a Kras-driven PDAC model, we observed reduced survival, increased tumor cell proliferation, enhanced aggression, and heightened inflammation." (PMID 40810725, 2025). "Using a Snx10 knockout PDAC mouse model, we observed significantly increased tumorigenesis, tumor size, and aggressiveness, particularly in KPCSfl/fl mice." (PMID 40810725, 2025). "In malignant disease, SNX10 has been reported to be downregulated in gastrointestinal malignancies, including PDAC, suggesting a potential tumor suppressor function." (PMID 40810725, 2025). "Paradoxically, a group of proteins, including C1QL3, EPB41, SNX10, FGF14, GLB1L2 and TRAK2, have been reported as good prognostic markers or tumor suppressors in the NmFMC group." (PMID 38951817, 2024). "Taken together, these results show that GSCs preferentially express SNX10 compared with nonneoplastic neural cells or differentiated tumor cells." (PMID 36795488, 2023). "The results suggested that, the high expression of C1orf74, HK2, SLC22A3, SNX10 and URB2 and Neutrophils, as well as the low expression of RASSF5 and CD8+ T cells was related to the poor prognosis of CC patients, which might serve as the key prognostic biomarkers of tumor." (PMID 36354693, 2022). "Thus, SNX10 is a GSC-specific vulnerability for cell proliferation and survival relative to nonneoplastic NSCs, differentiated tumor cells, and nonmalignant neural cultures." (PMID 36795488, 2023).
cancer (6 papers, 2018 to 2025). A tumor composed of atypical neoplastic, often pleomorphic cells that invade other tissues. "Despite mounting evidence linking SNX10 to various aspects of cancer, its role in B-ALL remains undetermined, to the best of our knowledge." (PMID 40341994, 2025). "IHC staining data comprising sections from cancer TMAs, sourced from the Human Protein Atlas database, confirmed a progressive decline in Snx10 protein expression as cancer advanced compared with normal tissues." (PMID 40810725, 2025). "Increasing evidence suggests that SNX10 also plays complex roles in cancer." (PMID 40341994, 2025). "As a relatively recently identified cancer regulator, the specific mechanism of action of SNX10 in B-ALL has not been assessed previously." (PMID 40341994, 2025). "To understand the role of SNX10 in GSC biology, we leveraged the Cancer Therapeutics Response Portal (CTRP), in which cellular proliferation responses to 481 compounds across 860 cancer cell lines were tested with gene expression data." (PMID 36795488, 2023).
infection (5 papers, 2015 to 2025). The state of being infected such as from the introduction of a foreign agent such as serum, vaccine, antigenic substance or organism. "We first examined the co-localization of L. monocytogenes with Rab7, a marker of late endosomes and phagosomes, in both control cells and SNX10 knockdown cells after infection." (PMID 28903313, 2017). "To determine whether SNX10 controls L. monocytogenes in vivo, we investigated the bacterial burden of liver and spleen from WT and Snx10-/- mice at 24 and 72 h after infection." (PMID 28903313, 2017). "Finally, infection of Snx10 KD splenocytes with a retrovirus expressing Snx10 reintroduced Snx10 expression and corrected the pit formation defect (2.25 +/− 0.62 mm2 n = 6, p = 0.008), confirming that Snx10 deficiency is responsible for the resorption defect." (PMID 25811986, 2015). "We next asked if depletion of Rab5A, SNX3 or SNX10 in CEM.CCR5 cells inhibits HIV-1 fusion and infection by modulating the virus uptake." (PMID 30691001, 2019). "The inhibition of HIV-1 fusion and infection in cells depleted of Rab5A, SNX3 or SNX10 suggests that this virus enters CEM.CCR5 cells via an endocytic pathway." (PMID 30691001, 2019). "The requirement for Rab5A, SNX3 and SNX10 for efficient HIV-1 fusion and infection in CEM.CCR5 cells suggests that endocytosis plays a role in productive entry into these cells." (PMID 30691001, 2019). "Next, we detected the expression of SNX10 in BMDMs after infection with Gram-negative bacteria (E. coli and Salmonella typhimurium) and Gram-positive bacteria (L. monocytogenes)." (PMID 28903313, 2017).
colorectal (2 papers, 2022). "Further analysis into the mechanism of SNX10 driven colorectal tumorigenesis revealed that loss of SNX10 activates chaperone-mediated autophagy (CMA) and increases the degradation of tumor suppressor p21 in a CMA dependent manner." (PMID 36612066, 2022).
bacterial infection (1 paper, 2017). "The overexpression of SNX10 induced the formation of giant late endosomes, and the deficiency of it led to a reduction in late endosomes and phagosomes during bacterial infection." (PMID 28903313, 2017). "Furthermore, we found that SNX10 interacted with the Mon1-Ccz1 complex, and loss of SNX10 reduced the recruitment of this complex to phagosomes and endosomes during bacterial infection." (PMID 28903313, 2017). "In our study, we found that SNX10 was highly expressed in mouse macrophages and was upregulated upon bacterial infection, which suggested a possible role of SNX10 in the anti-bacterial response of macrophages." (PMID 28903313, 2017). "Previous studies have demonstrated that SNX10 regulate endosomal morphology in mammalian cells, suggesting a possible role of SNX10 in regulating endocytosis pathway during bacterial infection in macrophage." (PMID 28903313, 2017). "Considering that SNX10 promotes bactericidal activity in macrophages, we wonder whether SNX10 results in an alteration in the endocytosis pathway during bacterial infection." (PMID 28903313, 2017). "Although some SNX family proteins, such as SNX3 and SNX5, have been shown to affect phagocytosis, our results suggested that SNX10 deficiency did not affect the phagocytosis of macrophages following bacterial infection." (PMID 28903313, 2017). "Considering that phagosomes acquire various hydrolases and undergo a progressive acidification during the course of maturation, we investigated whether SNX10 promotes phagosomal acidification upon bacterial infection." (PMID 28903313, 2017). "Thus, this study revealed an essential role of SNX10 in controlling bacterial infection." (PMID 28903313, 2017).
cardiac disease (1 paper, 2021). "SNX10 knockdown in zebrafish results in heart looping randomized, suggesting its potential role in heart disease." (PMID 33594863, 2021). "The regulatory mechanism of SNX10 in cardiac disease remained unknown." (PMID 33594863, 2021). "However, little has been reported about the role of SNX10 in cardiac disease." (PMID 33594863, 2021). "Sorting nexin 10 (SNX10) has been reported to be an important regulator in embryonic development and human diseases, however, little is known about its role in cardiac disease." (PMID 33594863, 2021). "Decreased SNX10 expression was related with AF and higher levels of the fibrosis degree, NYHA degree, LA diameter, and RA diameter, suggesting the important role of SNX10 in cardiac disease." (PMID 33594863, 2021). "Decreased SNX10 expression was related to AF and higher levels of fibrosis degree, NYHA degree, LA diameter, and RA diameter, suggesting the important role of SNX10 in cardiac disease." (PMID 33594863, 2021).
SNX10 also shares sentences with these, for which no sentence is quoted: osteoporosis (2 papers); acute B lymphoblastic leukemia (1); atrial fibrillation (1); cardiovascular diseases (1); cervical cancer (1); cervical squamous cell carcinoma (1); endometrial stromal sarcoma (1); fibrosis (1); Hydrocephalus (1); hypersplenism (1); lipid metabolism disorders (1); liposarcoma (1); Listeria monocytogenes infection (1); liver (1); melanoma (1); myopia (1); Nystagmus (1); optic atrophy (1); prostate tumor (1); skeletal dysplasia (1); stomach adenocarcinoma (1); stomach cancer (1).